ARMCX5 (armadillo repeat containing X-linked 5)
Synonyms: FLJ12969; GASP5
Tractability: Antibody: the Human Protein Atlas places it where antibodies can reach. PROTAC: ubiquitination databases record sites on it.
Gene: Protein-coding gene on chromosome X (102,599,168 to 102,604,159, forward strand). Ensembl gene ENSG00000125962.
Subcellular location (Human Protein Atlas): Cytosol; Nuclear speckles; Plasma membrane
Gene Ontology:
Molecular function: protein binding
Homologues: Orthologues: chimpanzee ARMCX5 (99% identical), macaque ARMCX5 (95% identical), rabbit ARMCX5 (75% identical), pig ARMCX5 (71% identical), rat Armcx5 (61% identical), mouse Armcx5 (61% identical), zebrafish armc10 (12% identical), tropical clawed frog armc10 (11% identical), Caenorhabditis elegans Y67A10A.7 (8% identical). Paralogues in human: GPRASP1 (29% identical), ARMCX4 (29% identical), GPRASP2 (29% identical), GPRASP3 (25% identical), ARMCX3 (17% identical), ARMCX1 (16% identical), ARMC10 (16% identical), ARMCX2 (15% identical), ARMCX6 (10% identical), ARMC12 (7% identical).
Diseases named in the same sentence as ARMCX5 in open-access papers:
ARMCX5 is named in the same sentence as 8 diseases in open-access papers, as found by Europe PMC text mining. Sharing a sentence is not in itself a finding about the gene and the disease. The quoted sentences say what the papers report.
Autoimmunity (1 paper, 2025). The occurrence of an immune reaction against the organism's own cells or tissues. "Abnormal immune cell death is a hallmark of autoimmunity, and it is possible that the ARMCX5-GPRASP2 readthrough (ARMCX5-GPRASP2, Gene ID: 100528062) gene is GD-associated." (PMID 39891056, 2025).
breast carcinoma (1 paper, 2025). "The enrichment of mutations in NDUSF1 and ARMCX5 in high-grade tumors potentially indicates their role in the metastasis of breast carcinomas." (PMID 41503337, 2025). "Additionally, this study highlights two understudied genes in breast carcinoma - ARMCX5 and SLCO6A1." (PMID 41503337, 2025). "Consistent with these advancements, our analysis reveals SETDB1, NDUFS1, ARMCX5, TRPM4, and SLCO6A1 as significantly altered genes in high-grade breast carcinomas." (PMID 41503337, 2025). "The TCGA-BRCA cohort analysis emphasizes a potential interplay of metabolic genes like NDUFS1, TRPM4, ARMCX5, SLCO6A1, and epigenetic axis genes like SETDB1 and USP37 in the oncogenesis and prognosis of breast carcinomas." (PMID 41503337, 2025).
epilepsy (1 paper, 2022). A brain disorder characterized by episodes of abnormally increased neuronal discharge resulting in transient episodes of sensory or motor neurological dysfunction, or psychic dysfunction. "ARMCX5, located on chromosome Xq22.1, a region associated with epilepsy 66, but there was no study in AD." (PMID 34975305, 2022).
gastric tumors (1 paper, 2020). "However, conversely, ARMCX5 was less expressed in normal gastric tissues than in primary gastric tumors." (PMID 32685472, 2020).
rheumatoid arthritis (1 paper, 2020). A chronic, systemic autoimmune disorder characterized by inflammation in the synovial membranes and articular surfaces. "Studies have shown that ARMCX5 can be activated by binding to the oncogene ZnF217 and ARMCX6 upexpressed at least 2-fold in peripheral blood monocytes of rheumatoid arthritis patients compared to those identified using oligonucleotide array." (PMID 32685472, 2020).
tumor (1 paper, 2025). "ARMCX5, a mitochondrial trafficking protein, was mutated in about 4.1% of grade IV tumours and 0.7% of grade II-III tumors." (PMID 41503337, 2025). "This pattern suggests that both ARMCX5 and SLCO6A1 have a plausible role in tumor aggressiveness and therapeutic resistance." (PMID 41503337, 2025).
ARMCX5 also shares sentences with these, for which no sentence is quoted: Alzheimer disease (1 paper); neurodegenerative disease (1).